PDIA3 (protein disulfide isomerase family A member 3)
Diseases named in the same sentence as PDIA3 in open-access papers (continued):
Sharing a sentence is not in itself a finding about the gene and the disease.
lymph node metastasis (6 papers, 2012 to 2023). "We found that the positive expression of CCT2 and PDIA3 was significantly associated with clinicopathological features of both SC/ASC and AC specimens, including high TNM stage and lymph node metastasis." (PMID 23782473, 2013). "High expression of MYC was associated with advanced pTNM-stage (P=0.011), and PDIA3 and ITGA5B1 were correlated with both lymph node metastasis (PDIA3: P < 0.001; ITGA5B1: P=0.001) and pTNM-stage (PDIA3: P=0.001; ITGA5B1: P=0.009)." (PMID 31886273, 2019). "PDIA3 expression was higher in the group without lymph node metastasis compared to the group with lymph node metastasis (χ2 = 5.593, P = 0.018)." (PMID 37909009, 2023). "Moreover, a higher expression of PDIA3 significantly correlated with higher TNM stage, adjacent tissue invasion, and lymph node metastasis (P < 0.05)." (PMID 23782473, 2013).
Parkinson disease (5 papers, 2015 to 2021). A progressive degenerative disorder of the central nervous system characterized by loss of dopamine producing neurons in the substantia nigra and the presence of Lewy bodies in the substantia nigra and locus coeruleus. "PDIA3 is also involved in several cellular functions and consequently associated with different human diseases such as cancer, prion disorders, Alzheimer’s and Parkinson’s diseases." (PMID 30658391, 2019). "The bioactivity of the extracts was tested on the redox activity of PDIA3 disulfide isomerase, an enzyme involved in the regulation of several cellular functions and associated with different diseases such as cancer, prion disorders, Alzheimer’s and Parkinson’s diseases." (PMID 30658391, 2019).
squamous cell carcinoma (5 papers, 2021 to 2025). A carcinoma arising from squamous epithelial cells. "Previously, it was shown that deletion of the PDIA3 gene in the A431 squamous cell carcinoma line (A431ΔPDIA3) affected expression of more than 1800 genes, including genes modulated by 1,25(OH)2D3 treatment." (PMID 38201216, 2023). "Here, we investigated an impact of PDIA3 in mitochondrial morphology and bioenergetics in squamous cell carcinoma line A431 treated with 1,25(OH)2D3." (PMID 37960182, 2023). "The present study aimed to assess the impact of PDIA3 on morphology and bioenergetics of mitochondria and its role in 1,25(OH)2D3 action on mitochondria in squamous cell carcinoma A431 cell line." (PMID 37960182, 2023). "Lately, it has been shown that PDIA3 knockout in squamous cell carcinoma alters the expression of the genes connected to the regulation of bone mineralization, phospholipase C activity, and calcium-dependent phospholipid binding." (PMID 38201216, 2023). "Here, the impact of PDIA3 deletion on mitochondrial morphology and bioenergetics in squamous cell carcinoma (A431) and its potential role in the action of vitamin D on mitochondria were investigated for the first time." (PMID 37960182, 2023). "In conclusion, this study demonstrated that both VDR and PDIA3 are needed to regulate membrane response to active forms of vitamin D in A431 squamous cell carcinoma, possibly through CAMKIIα and impaired calcium influx, respectively." (PMID 38201216, 2023). "Here, we showed the deletion of either VDR or PDIA3 decreased baseline calcium levels in squamous cell carcinoma A431 cells and further impaired calcium influx induced by 1,25(OH)2D3." (PMID 38201216, 2023). "Taken together, our results presented here emphasize the importance of PDIA3 in 1,25(OH)2D3 signaling in squamous cell carcinoma cell line A431." (PMID 38201216, 2023). "Moreover, it seems that VDR and PDIA3 are required for the regulation of calcium influx induced by 1,25(OH)2D3 in squamous cell carcinoma." (PMID 38201216, 2023). "Thus, this study focused on a squamous cell carcinoma cell line with deletion of PDIA3 (A431∆PDIA3) as a model." (PMID 37960182, 2023). "The deletion of PDIA3 not only affected membrane signaling but also genomic responses to vitamin D. Moreover, it seems that both VDR and PDIA3 are required for the regulation of calcium signaling induced by 1,25(OH)2D3 in A431 squamous cell carcinoma." (PMID 38201216, 2023). "Complementary to our previous research on the topic of non-genomic responses to 1,25(OH)2D3 in squamous cell carcinoma, we further explored the role of PDIA3 in calcium homeostasis and membrane signaling after 1,25(OH)2D3 treatment." (PMID 38201216, 2023). "In our latest studies, we investigated the impact of deletion of either VDR or PDIA3 on gene expression profile and non-genomic effects of 1,25(OH)2D3 in A431 squamous cell carcinoma, showing that PDIA3 is involved in genomic responses to 1,25(OH)2D3." (PMID 38201216, 2023). "Here, the role of VDR and PDIA3 proteins in membrane response to 1,25(OH)2D3 and calcium signaling was investigated in squamous cell carcinoma A431 cell line with or without the deletion of VDR and PDIA3 genes." (PMID 38201216, 2023).
thyroid cancer (5 papers, 2019 to 2023). "The results of this study showed that the PDIA3 gene was highly expressed in 19 types of tumor tissues and only lowly expressed in thyroid cancer tumor tissues." (PMID 36046686, 2022). "In thyroid carcinoma, PDIA3 expression was down-regulated in tumor tissues compared with normal tissues." (PMID 36406049, 2022). "On the contrary, compared with normal tissues, the expression of PDIA3 in thyroid carcinoma (THCA) is downregulated." (PMID 36046686, 2022).
invasive breast carcinoma (4 papers, 2020 to 2023). A carcinoma that infiltrates the breast parenchyma. "In an analysis of PDIA3 gene expression based on RNASeq data in the TNMplot database, we confirmed that PDIA3 expression is typically elevated in invasive breast cancers versus normal tissue." (PMID 36374169, 2023).
leukemia (4 papers, 2019 to 2025). A malignant (clonal) hematologic disorder, involving hematopoietic stem cells and characterized by the presence of primitive or atypical myeloid or lymphoid cells in the bone marrow and the blood. "Druggability evaluation of the 12 identified risk proteins revealed that three (AXL, CXCL8, and PDIA3) are already recognized as drug development targets for leukemia, cancer, and inflammation." (PMID 41463415, 2025).
liver cancer (4 papers, 2019 to 2023). An epithelial or non-epithelial malignant neoplasm that arises from the liver. "Very recently it has been reported that 16F16, a PDIA3 inhibitor, enhances the antiproliferative effect of the mTOR inhibitor everolimus in liver cancer." (PMID 36769334, 2023). "For example, biological targets identified in human liver cancer cells using a library of tagged C75 analogs revealed previously unknown putative C75 targets, including protein disulfide-isomerase A3 (PDIA3), transferrin receptor (TRFC), and glyceraldehyde-3-phosphate dehydrogenase (GAPDH)." (PMID 31681794, 2019).
male infertility (4 papers, 2010 to 2024). The inability of the male to effect fertilization of an ovum after a specified period of unprotected intercourse. "In this context, PDIA3, MANF, PDIA3, GRP78, and CRT emerge as particularly promising candidates for further investigation and potential clinical application in the diagnosis of male infertility." (PMID 39237030, 2024). "The areas under the curve and P-values calculated from the ROC curve analysis suggest that PDIA3, MANF, GRP78, and CRT could serve as potential biomarkers for diagnosing male infertility." (PMID 39237030, 2024).
stomach tumors (4 papers, 2006 to 2023). "Celli and Jaiswal confirmed that the content of transcripts of encoding PDIA3/ERp57 in breast, uterus, lung, and stomach tumors was higher than that in the corresponding normal tissues." (PMID 36046686, 2022).
airway hyperresponsiveness (3 papers, 2013 to 2022). "PDIA3 ablation or inhibition resulted in decreases in allergic airway inflammation, airway hyperresponsiveness, peribronchiolar fibrosis, and pulmonary fibrosis." (PMID 35162999, 2022). "We also observed that PDIA3 depletion decreases influenza-induced apoptosis of lung epithelial cells and disulfide bonds in HA, leading to decrease in influenza burden and airway hyperresponsiveness." (PMID 35162999, 2022). "A study on ERp57/PDIA3 expressed in mouse lung epithelial cells suggested the importance of this protein in the formation of disulfide bonds of influenza A virus (IAV) hemagglutinin (HA) and the subsequent establishment of infection, inflammation, and airway hyperresponsiveness (AHR)." (PMID 35109791, 2022).
breast tumor (3 papers, 2020 to 2023). "The presence of PDIA3 was investigated in individual samples of primary human luminal and basal breast tumours by immunohistochemistry." (PMID 33095243, 2020). "Moreover, immunofluorescence staining of frozen breast tumor sections from tumor-bearing mice receiving CSSTRESAC-phage iv suggested co-localization between PDIA3 and CD68, a well-established cell surface marker of macrophages." (PMID 34060472, 2021). "From our observational immunohistochemical study on primary breast tumors, PDIA3 staining was apparent in the epithelial glandular structures, but not in the stroma, of a luminal-type tumor and generalized PDIA3 staining was detected in a basal-type tumor." (PMID 36374169, 2023).
gallbladder carcinoma (3 papers, 2013 to 2021). "Our study suggests that positive expression of CCT2 or PDIA3 is associated with tumor progression and the clinical behavior of gallbladder carcinoma." (PMID 23782473, 2013). "Although their clinical importance was well studied in other cancers, the expression of CCT2 and PDIA3 and their clinicopathological significance in gallbladder cancer have never been investigated." (PMID 23782473, 2013). "Therefore, the expression level of PDIA3 in AC and SC/ASC reflected the progression and clinical behavior of gallbladder cancer and might be an important biomarker of poor prognosis." (PMID 23782473, 2013).
infertile (3 papers, 2014 to 2024). "The Cohen's d values for markers such as PDIA3, MANF, and GRP78 were 1.633, 0.574, and 0.766, respectively, strongly supporting the association of these proteins with infertility." (PMID 39237030, 2024). "In our study, PDIA3 serum levels were found to be higher in infertile patients." (PMID 39237030, 2024). "The particularly high effect size for PDIA3 suggests that this protein could be a significant biomarker in cases of infertility." (PMID 39237030, 2024). "However in our study, the increased expression of PDIA3 during receptive phase/mid-secretory phase endometrium of infertile women might induce IL-11/STAT3 signalling pathway, which in turn cause proliferation and growth of endometrial cells." (PMID 25405865, 2014). "Specifically, we found that the levels of PDIA3, MANF, and CRT were increased in the infertile male group compared to the control group." (PMID 39237030, 2024). "Based on this review, we selected PDIA1, PDIA3, MANF, GRP78, CLU, CRT, and CNX as chaperones for validation as serum-based biomarkers in potentially infertile populations." (PMID 39237030, 2024). "Serum PDIA1 (P = 0.0004), MANF (P = 0.018), PDIA3 (P < 0.0001), GRP78 (P = 0.0027), and CRT (P = 0.0009) levels were higher in the infertile group compared to the control." (PMID 39237030, 2024). "In the analysis of the results from various GEO databases, it was observed that the mRNA expression levels of the human targets PDIA3, MANF, CLU, CRT, and CNX were decreased in the infertile male group compared to the control group, as reported in the respective data sets." (PMID 39237030, 2024).
non-small cell lung carcinoma (3 papers, 2017 to 2022). A group of at least three distinct histological types of lung cancer, including non-small cell squamous cell carcinoma, adenocarcinoma, and large cell carcinoma. "The combination of CALR and PDIA3 has also been suggested as a possible prognostic biomarker for non-small-cell lung cancer, with PDIA6 modulating apoptosis and autophagy of non-small-cell lung cancer cells via the MAP4K1/JNK signalling pathway." (PMID 36291587, 2022). "Interestingly, the combination of CALR and disulfide isomerase (PDIA3) was found to be a potential prognostic biomarker for non-small-cell lung cancer, which coincides with our finding of the upregulation of PDIA4 in ADC and PDIA3 and PDIA4 in SCC tissues." (PMID 35512017, 2022).
oral squamous cell carcinoma (3 papers, 2016 to 2023). "This study aimed to investigate the role of protein disulfide isomerase A3 (PDIA3) in oral squamous cell carcinoma (OSCC) and evaluate its significance as a diagnostic and prognostic biomarker." (PMID 38213579, 2023).
pancreatic cancer (3 papers, 2017 to 2021). "It has been found that PDIA3 and CALR are highly co-expressed in micrometastasis pancreatic cancer cell lines PC-1 and Capan-2." (PMID 34910788, 2021).
pulmonary fibrosis (3 papers, 2015 to 2022). Chronic progressive interstitial lung disorder characterized by the replacement of the lung tissue by connective tissue, leading to progressive dyspnea, respiratory failure, or right heart failure. "Moreover, in primary ATII cells from bleomycin-induced lung injury – a model exhibiting activated Wnt/β-catenin signaling and pulmonary fibrosis in vivo – CBR2 expression was reduced, significantly correlating with reduced pro-SFTPC, whereas ENO1, PDIA3 and T1α were increased." (PMID 26035385, 2015).
bipolar disorder (2 papers, 2016 to 2025). A disorder of the brain that causes unusual shifts in mood, energy, activity levels and the ability to carry out day-to-day tasks. "Furthermore, we also found multiple SNPs that localize to PDIA3, PDIA6 and HYOU1 that link to either BMI or bipolar disorder." (PMID 27280443, 2016).
brain injury (2 papers, 2022 to 2024). Acute and chronic (see also brain INJURIES, CHRONIC) injuries to the brain, including the cerebral hemispheres, CEREBELLUM, and brain STEM. "PDIA3-knockout models have been associated with less fibrosis in murine models of lung injury, muscle injury, and traumatic brain injury." (PMID 36509292, 2022).
chronic rheumatic heart disease (2 papers, 2021 to 2022). "Fae and collaborators demonstrated PDIA3 and HSPA5 to be recognized by heart infiltrating and peripheral T cells in chronic rheumatic heart disease patients, suggesting that these proteins may be involved in an autoimmune-mediated tissue response as autoantigen targets of antibodies." (PMID 34885011, 2021).
colon adenocarcinoma (2 papers, 2022 to 2023). "It was found that ATP5A1 and ENO1 were positively correlated with the infiltration of CD4+ T lymphocytes in colon adenocarcinoma and a negative correlation between GADPH and PDIA3 with the infiltration of NK cells and CD4+ T lymphocytes in rectal adenocarcinoma, respectively." (PMID 35445138, 2022).
diffuse large B-cell lymphoma (2 papers, 2022). "Then genomic alteration analysis of PDIA3 indicated that the alterations of PDIA3 across pan-cancer were not universal, and the most frequently altered cancer type was lymphoid neoplasm diffuse large B-cell lymphoma (DLBC), exceeding 6% DLBC patients and was mostly deep deletion." (PMID 35401558, 2022).
dyslipidemia (2 papers, 2022 to 2024). "This was also confirmed by the direct association of CALR and PDIA3 with the number of metabolic alterations typical of metabolic syndrome." (PMID 36213269, 2022). "CALR and PDIA3 could be early markers of insulin resistance and dyslipidemia-related ER stress useful to stratify patients at high risk of further complications." (PMID 36213269, 2022). "Both PDIA3 and CALR were positively associated with insulin resistance, cholesterol, and triglycerides and the number of criteria identifying metabolic syndrome and negatively with fasting and post-challenge insulin sensitivity." (PMID 36213269, 2022). "CALR and PDIA3 could be early markers of insulin resistance and dyslipidemia-related ER stress, being useful to stratify patients at high risk of further complications over time." (PMID 36213269, 2022).
esophageal cancer (2 papers, 2021 to 2022). A primary or metastatic malignant neoplasm involving the esophagus. "One such protein disulfide isomerase termed PDIA3 has been reported in esophageal cancers and plays a multifaceted role in cancers." (PMID 34830970, 2021).
gastric adenocarcinoma (2 papers, 2021 to 2022). "High levels of PDIA3 in gastric adenocarcinoma have been associated with better prognosis." (PMID 33620602, 2021).
hepatic disorders (2 papers, 2017 to 2021). "Overall, the upregulation of CDKN1A, NFKB2, RELB, and PDIA3 indicates a worse prognosis of liver disease and an impaired immune response against HIV." (PMID 33785040, 2021).
influenza (2 papers, 2020 to 2022). An acute viral infection of the respiratory tract, occurring in isolated cases, in epidemics, or in pandemics; it is caused by serologically different strains of viruses (influenzaviruses) designated A, B, and C, has a 3-day incubation period, and usually lasts for 3 to 10 days. "Here we report for the first time that PDIA3 inhibition disrupts disulfide bonds in influenza-NA, and ultimately its activity." (PMID 35162999, 2022).
Insulin resistance (2 papers, 2022 to 2024). Increased resistance towards insulin, that is, diminished effectiveness of insulin in reducing blood glucose levels. "Moreover, recent findings have suggested that calreticulin and protein disulfide isomerase family A member 3 (PDIA3), two markers for ERS, were associated with insulin resistance induced by childhood obesity." (PMID 40302954, 2024). "Our preliminary data suggest that CALR and PDIA3, two key molecules of ER stress, could be related to insulin resistance and altered lipid profile in pediatric obesity." (PMID 36213269, 2022).
metastatic prostate carcinoma (2 papers, 2009 to 2013). A carcinoma that arises from the prostate gland and has spread to other anatomic sites. "Taking our IHC data of PDIA3 into account, PDIA3 protein concentration decreases significantly in CA5 compared to CA4 tissues and expression data comparing localized with metastatic prostate cancer showed a down-regulation of PDIA3." (PMID 20035634, 2009).
myeloproliferative neoplasm (2 papers, 2020 to 2022). A clonal hematopoietic stem cell disorder, characterized by proliferation in the bone marrow of one or more of the myeloid (i.e., granulocytic, erythroid, megakaryocytic, and mast cell) lineages. "Another study identified ERp57/PDIA3 as being indirectly involved, with a mutant calreticulin gene (CALR), in altered Ca2+ mobilization in patients with myeloproliferative neoplasms." (PMID 35109791, 2022).
neuroectodermal tumors (2 papers, 2007 to 2017). "In fact, ERp57 (PDIA3) and ERdj5 (PDIA19) were consistently upregulated in both neuroectodermal tumors, with the abrogation of their expression, resulting in enhanced cell death induction under ER stress conditions." (PMID 28491820, 2017).
oligodendroglioma (2 papers, 2020 to 2023). A well-differentiated (WHO grade II), diffusely infiltrating neuroglial tumor, typically located in the cerebral hemispheres. "The high PDIA3 expression cluster frequently showed amplification of chr7 and deletion of chr10, both of which were typical genomic events in GBM; while deletion of 1p and 19q, a genomic hallmark of oligodendroglioma, occurred more frequently in PDIA3 low cluster." (PMID 32687065, 2020).
pancreatic adenocarcinoma (2 papers, 2020 to 2022). "However, PDIA3 expression levels were not significantly different between kidney chromophobe, kidney renal papillary cell carcinoma, pancreatic adenocarcinoma, and rectum adenocarcinoma cancers and those with only normal tissue samples." (PMID 36406049, 2022).
renal cell carcinoma (2 papers, 2022 to 2023). "Therefore, PDIA3 may become a new candidate marker for the diagnosis of renal cell carcinoma, which provides important significance for early clinical diagnosis of renal cell carcinoma." (PMID 36046686, 2022).